HMGA2 (high mobility group AT-hook 2)
Diseases named in the same sentence as HMGA2 in open-access papers (continued):
Sharing a sentence is not in itself a finding about the gene and the disease.
glioma (continued). "The Kaplan‐Meier and Cox's regression analysis results showed that higher HMGA2 level predicted the poorer outcomes of glioma patients." (PMID 29733521, 2018). "We also found that HMGA2 was an independent prognostic factor for glioma patient survival by multivariate and univariate analyses." (PMID 29733521, 2018). "Although HMGA2 overexpression has been detected in different malignant tissues, the oncogenic mechanism and clinical relevance of HMGA2 in gliomas remained unclear." (PMID 29733521, 2018). "The results showed that the HMGA2 level was significantly and positively correlated with glioma grade and was highest in GBM." (PMID 29733521, 2018). "The results further enriched our understanding of the mechanism by which HMGA2 regulates the malignant phenotype of gliomas." (PMID 29733521, 2018). "IHC analysis of mouse allografts, xenografts derived from human U87MG glioma cells, and human GB tissues all showed nuclear HMGA2 expression exclusively in GB cells." (PMID 28500786, 2017). "We observed a further dramatic increase in γH2AX foci in HMGA2‐silenced GB cells upon TMZ treatment, indicating significant dsDNA damage in HMGA2‐depleted glioma cells." (PMID 28500786, 2017). "Although HMGA2 depletion has little effects on proliferation of regular glioma cells, it's essential for self-renewal of GICs." (PMID 27259253, 2016). "Consistently, HMGA2 is ubiquitously co-expressed with SOX2 in adherent cultured glioma-initiating cells (GICs)." (PMID 27259253, 2016). "In this study, we unveiled that HMGA2 is highly expressed in mesenchymal GBMs, labels glioma-initiating cells (GICs) and glioma pericytes." (PMID 27259253, 2016). "We therefore checked HMGA2 expressions in various glioma specimens (6 WHO grade I, 12 grade II, 4 grade III, 13 Grade IV/GBMs) and 5 normal brain tissues on a tissue array using immunohistochemistry followed by quantitation." (PMID 27259253, 2016). "In this study, we found the expression of RKIP and miR-98 in glioma tissues was significantly lower and HMGA2 was higher than that in normal brain tissues." (PMID 24392454, 2013). "We performed SYBR green quantitative PCR analysis to detect the expression level of RKIP, HMGA2, and miR-98 in glioma tissues and cell lines." (PMID 24392454, 2013). "Our findings newly described RKIP/miR-98 to HMGA2 link and provided a potential mechanism for glioma cell invasion." (PMID 24392454, 2013). "Additionally, we further revealed that HMGA2 can be a novel significant prognostic biomarker in glioma and function as a potential therapeutic target for glioma." (PMID 40351420, 2025). "Furthermore, high HMGA2 expression serves as an independent prognostic factor for poor survival in glioma patients." (PMID 40351420, 2025). "These collectively indicated that HMGA2 promotes malignant progression in gliomas." (PMID 40351420, 2025). "Moreover, to further identify the potential immunotherapy strategy of glioma targeting COL4A factors and HMGA2, immunomodulators associated with COL4A factors and HMGA2 were retrieved from the online database TISIDB." (PMID 40351420, 2025). "In summary, our study revealed a potential common target of COL4A members HMGA2, which could serve as a novel prognostic factor for the diagnosis and therapy of glioma." (PMID 40351420, 2025). "By being involved in the infiltration of Th2 cells and macrophages, HMGA2 could serve as an independent prognostic biomarker for glioma." (PMID 40351420, 2025). "Further study has found that LinC00319 can directly bind to TATA box binding protein related factor 1 (TAF1) and further regulate HMGA2 to promote glioma cell proliferation, accelerate cell cycle, and inhibit glioma cell apoptosis, providing new ideas for molecular targeted therapy of glioma." (PMID 38967893, 2024). "HMGA2 increases glioma cell migration in part by increasing MMP-2." (PMID 37370851, 2023). "HMGA2 expression correlates directly with tumor grade and indirectly with survival in glioma." (PMID 37370851, 2023).
glioma (continued). "Also, miR-34a-5p inhibited tumorigenesis and progression of gliomas by targeting high-mobility group AT-hook 2 (HMGA2)." (PMID 35444864, 2022). "In contrast, IL33oe increased H2A and H3 proteins and HMGA1 and HMGA2 in glioma cells." (PMID 34744630, 2021). "Furthermore, a previous investigation also suggested that the expression of HMGA2 significantly correlated with the invasion and survival of glioma cells." (PMID 33519932, 2021). "FOXD2-AS1 could also promote glioma progression by regulating the miR-185-5p/high-mobility group AT-hook 2 (HMGA2) axis and the PI3K/AKT signaling pathway." (PMID 33336050, 2020). "Moreover, HMGA2 was up-regulated in glioma tissues than in normal brain tissues, suggesting its potential role as a functional target of let-7a via binding of the 3′-UTR." (PMID 32432318, 2020). "Our results showed that the HMGA2 level was remarkably and positively correlated with glioma grade in our 147 glioma specimens, indicating that HMGA2 may act as a promising biomarker to distinguish the WHO grades of glioma." (PMID 29733521, 2018). "We identified 20 GSC-upregulated miRNA-targeted genes associated with significantly reduced 5-year survival in GBM patients, including previously identified glioma-promoting genes HMGA2, MYO1C, RGS4, and several novel targets, such as HPCAL1, IMPDH1, and YWHAG (orange-colored genes)." (PMID 29587824, 2018). "Transwell and orthotopic implantation were used to investigate the roles of HMGA2 in glioma cells." (PMID 29733521, 2018). "FoxM1 might be in turn upregulated by high-mobility group AT-hook 2 (HMGA2), a protein that was demonstrated to be highly expressed in Grade II-IV gliomas, supporting GBM cell invasive behavior." (PMID 29261132, 2017). "Here we found HMGA2, an architectural transcription factor that promotes mesenchymal phenotypes in a number of solid tumors, is highly expressed in mesenchymal subtype of GBMs and labels both glioma pericytes and glioma-initiating cells (GICs)." (PMID 27259253, 2016). "We next studied HMGA2′s function in promoting mesenchymal phenotypes and invasiveness in gliomas." (PMID 27259253, 2016). "The high expression of HMGA2 in glioma-initiating cells/glioma stem cells/tumor propagating cells (GICs/GSCs/TPCs) prompted us to examine whether HMGA2 is essential for GIC propagating (self-renewal) and tumorigenicity." (PMID 27259253, 2016). "Immunoblotting was performed to detect the expression of RKIP and HMGA2 in glioma cell lines." (PMID 24392454, 2013). "Additionally, we find that RKIP inhibits miR-98 target gene HMGA2 which enhances invasion and regulates a number of target genes that contribute to invasion and metastasis in the glioma cell lines." (PMID 24392454, 2013). "Thus, HMGA2 involved in immune infiltration in glioma may play a critical role in the effects of the COL4A family on patient prognosis." (PMID 40351420, 2025). "Therefore, combining with the previous results, we concluded that the PDL-1 and GITR function-related immune cells in glioma were also highly associated with COL4As and HMGA2, which further confirmed the effects of COL4As and their target factor HMGA2 on glioma progress." (PMID 40351420, 2025). "Thus, HMGA2 may be a critical factor for COL4A family members involved in glioma progression and a potential therapeutic target of glioma." (PMID 40351420, 2025). "Notably, we observed elevated HMGA2 expression levels in glioma tissues." (PMID 40351420, 2025). "Due to the tumor-infiltrating lymphocytes are the independent predictors of sentinel lymph node status and patients’ survival in cancer, we speculated that COL4As and HMGA2 may influence the patients’ prognosis by involving in the immune infiltration of glioma." (PMID 40351420, 2025). "Moreover, we determined that HMGA2 could predict the poor prognosis of glioma patients and that HMGA2 might act as novel subclassification diagnosis factor." (PMID 29733521, 2018).
glioma (continued). "Moreover, high HMGA2 expression levels correlate with shorter survival time in glioma patients using the CGGA (The Chinese Glioma Genome Atlas) dataset, which is consistent with reports showing higher levels of IL-6/HMGA2/SOX2 expression indicated shorter overall survival period in GBM patients." (PMID 27259253, 2016). "Therefore, pericytes in gliomas could be stem-like cell pools and it would be tempting to explore if HMGA2 is key to regulating the fate switch between the two cell populations." (PMID 27259253, 2016). "Since GICs can generate glioma pericytes, we postulate HMGA2 might have a role in this process." (PMID 27259253, 2016). "Moreover, HMGA2 expression is positively correlated with expressions of STAT3 and C/EBPβ, two essential transcription factors that promote mesenchymal phenotypes in GBMs; as well as that of CD44, another hallmark of glioma invasiveness." (PMID 27259253, 2016). "Together with the increase in Hmga2 and the inability to differentiate, this raises the question as to whether Dicer-null NS cells are transformed in some manner, or bear similarities with glioma cells." (PMID 20976144, 2010). "For instance, Foxd2-as1/miR-185-5P/HMGA2 axis influences the PI3K/Akt signaling pathway to promote tumorigenesis and progression of glioma." (PMID 32735016, 2020). "miR-98 was shown to downregulate HMGA2 expression in glioma cells as a part of the RKIP/miR-98/HMGA2 axis, leading to a reduction in glioma cell invasion." (PMID 31979076, 2020). "For example, FOXD2‐AS1 acts as a sponge of miR‐185‐5p to regulate HMGA2 and influence the PI3K/Akt signalling pathway in glioma." (PMID 33098266, 2020). "Moreover, we identified HMGA2 could predict poorer prognosis of gliomas independent of other factors, such as IDH mutation." (PMID 29733521, 2018). "Our results showed increased expression of the HMGA2 protein in the majority of both GBM and WHO grade I‐III glioma tumors by IHC using a cohort of 147 grade I‐IV gliomas compared to 20 normal brain samples." (PMID 29733521, 2018). "Mechanistically, we first discovered that HMGA2, together with GCN5, facilitated the invasion of glioma cells via inducing chromatin conformational remodeling of the MMP2 gene promoter and epigenetically activating MMP2 gene transcription." (PMID 29733521, 2018). "TCGA data analysis revealed increased gene expression of HMGA2 in the mesenchymal GB subtype compared to the glioma CpG island methylator phenotype (G‐CIMP subtype) and up to 2% of GB patients harbor HMGA2 gene amplifications as determined by cBioPortal." (PMID 28500786, 2017). "Patient GB cells isolated from GB tumors and the human glioma cell lines U251 and U87MG expressed HMGA2 transcripts, and we confirmed the nuclear localization of HMGA2 protein in GB cells by western blot analysis." (PMID 28500786, 2017). "In U87MG glioma cells, overexpression of either HMGA1 or HMGA2 or both significantly enhances luciferase activities driven by the two promoters." (PMID 27259253, 2016). "First, FOXM1 expression levels are positively correlated with HMGA2 expression in GBM specimens from the TCGA dataset and glioma samples from the CGGA dataset." (PMID 27259253, 2016). "In contrast to neglected HMGA2 expressions in normal brain tissues (NAT), profound HMGA2 expression can be seen in glioma samples, especially in WHO Grade II-IV gliomas." (PMID 27259253, 2016). "We further quantitated HMGA2 densities to take into account denser cellularity in gliomas, and detected significant stronger HMGA2 signals in Grade III and Grade IV (GBM) gliomas." (PMID 27259253, 2016). "Using qRT-PCR, we confirmed that the expression levels of FOXM1, PLAU, CYR61, THBS1 and ADAM9 are indeed significantly down-regulated upon HMGA2 depletion in TPC1115 GICs, U87MG glioma cells and SK-N-SH neuroblastoma cells." (PMID 27259253, 2016).
glioma (continued). "In the present study, we found that HMGA2 was also mainly involved in proliferation (PI3K-Akt pathway), invasion and migration (protein digestion and absorption and ECM-receptor interaction) in glioma, which is consistent with the function of the COL4A family." (PMID 40351420, 2025). "Among the seven key genes (HOXD11, HOXC9, HOXC6, HOXA3, FBXO39, OTP, and HMGA2) consistently detectable in both normal astrocyte cell lines (SVG-P12) and glioma cell lines (U87, U251, LN229), tumor cell lines exhibited significantly upregulated expression compared to normal cell lines." (PMID 41049291, 2025). "As previously reported, LINC00319 directly binds to TAF‐1 and further regulates HMGA2 in gliomas, leading us to hypothesize that lncRNA FOXD2‐AS1 is involved in glioma via TAF‐1 and the NOTCH signalling pathway." (PMID 35419917, 2022). "To investigate whether the correlations between HMGA2 and MMP2 exist in human glioma tissues, we further detected MMP2 in our FFPE specimens by IHC and compared its expression pattern with that of HMGA2." (PMID 29733521, 2018). "Our results indicated that HMGA2, as a novel GCN5 recognition partner and histone acetylation modulator, may be novel prognostic indicator and promising glioma treatment target." (PMID 29733521, 2018). "RKIP overexpression in glioma cell lines was found to increase the expression of miR-98, which in turn inhibits its target gene HMGA2, resulting in decreased glioma cell invasion but without affecting tumor cell proliferation rates." (PMID 30149591, 2018). "Similarly, PLAU is highly expressed in GBM specimens, and its expression level is positively correlated with HMGA2 expression in GBM specimens and inversely correlated with glioma patients' survival period." (PMID 27259253, 2016). "Therefore, HMGA2 was involved in the similar function with COL4A factors, and may service as a key factor for glioma progression." (PMID 40351420, 2025). "let-7b has suspected tumor suppressor function in gliomas and low expression of the let-7 family members may be responsible for the poor prognosis of brain tumors patients through disturbed inhibition of KRAS, HMGA2 and MYC oncogenes." (PMID 31170943, 2019). "MMP2, not as precise as HMGA2, could still auxiliarily indicate glioma poor prognosis." (PMID 29733521, 2018). "We detected HMGA2 expression in all FFPE specimens by IHC staining, including 147 glioma and 20 nontumoral brain tissue samples." (PMID 29733521, 2018).
hepatocellular carcinoma (44 papers, 2013 to 2025). A malignant tumor that arises from hepatocytes. "Additionally, recent TCGA meta-analysis has revealed a significant association between HMGA2 overexpression and poor overall survival in 14 types of cancers, including hepatocellular carcinoma." (PMID 32577156, 2020). "It has been reported to play an oncogenic role in colon cancer through the HMGA2 axis and to promote hepatocellular carcinoma through the PTEN pathway." (PMID 40360483, 2025). "Circular RNA nuclear factor IX (circNFIX) facilitates hepatocellular carcinoma (HCC) development via targeting the miR-3064-5p-HMGA2 axis." (PMID 37234708, 2023). "In another study concerning hepatocellular carcinoma, YTHDC1 favored the cytoplasmic export of m6A modified circHPS5 which acted as a miR-370 sponge to downregulate the expression of HMGA2 and thus accelerate the hepatocellular carcinoma tumorigenesis." (PMID 35501308, 2022). "HMGA2 expression is undetectable in adult tissues, and it is significantly overexpressed in different cancers as hepatocellular carcinomas, esophageal squamous cell carcinoma, tongue squamous cell carcinoma, and thyroid carcinoma." (PMID 34439740, 2021). "CircZFR exerted the oncogenic function in hepatocellular carcinoma by affecting the miR-375-mediated HMGA2 expression." (PMID 34174955, 2021). "MiR-9 is another type of microRNA that mediates antitumor activities on hepatocellular carcinoma progression directly targeting HMGA2." (PMID 34439740, 2021). "For clear cell renal cell carcinoma, head and neck cancer, hepatocellular carcinoma, and pancreatic ductal adenocarcinoma, patients with high HMGA2 expression have shorter overall survivals." (PMID 31581665, 2019). "It was reported that CCAT1 functioned as a molecular sponge for let-7, up-regulated expression of its endogenous targets HMGA2 and c-Myc, and inhibited its function in hepatocellular carcinoma." (PMID 30683807, 2019). "Patients with high expressed HMGA2 in ccRCC, head and neck cancer, hepatocellular carcinoma and pancreatic ductal adenocarcinoma showed a significant shorter OS than patients with a low level of HMGA2 expression." (PMID 29997523, 2018). "To better understand the significance of HMGA2-sh-3p20 in hepatoma cells, we examined the effect of HMGA2-sh-3p20 on proliferation of hepatoma cells by MTT, EdU, colony-formation and flow cytometry assays in HepG2 (or Huh7) cells." (PMID 28522832, 2017). "A previous study found that miR-1297 promoted apoptosis and inhibited the proliferation and invasion of hepatocellular carcinoma cells by targeting HMGA2." (PMID 28396617, 2017). "Strikingly, we observed that TTP was capable of interacting with HMGA2 mRNA, resulting in the decrease of HMGA2 in hepatoma cells." (PMID 28522832, 2017). "Strikingly, we show that HMGA2-sh-3p20 upregulates the expression of HMGA2 through antagonizing TTP-mediated HMGA2 degradation in hepatoma cells." (PMID 28522832, 2017). "Mechanistically, RNA immunoprecipitation assays showed that the microprocessor Drosha or DGCR8 interacted with HMGA2 mRNA in hepatoma cells." (PMID 28522832, 2017). "Next, we identified the mechanism by which HMGA2-sh-3p20 upregulated the expression of HMGA2 in hepatoma cells." (PMID 28522832, 2017). "Significantly, we documented the ability of HMGA2-sh-3p20 to promote the growth of hepatoma cells in vitro and in vivo." (PMID 28522832, 2017). "Our data showed that the fragment HMGA2-sh-3p20 from HMGA2 mRNA 3′UTR promotes the growth of hepatoma cells by upregulating HMGA2." (PMID 28522832, 2017). "In human liver carcinoma cells, High Mobility Group AT-Hook 2 (HMGA2) binds to Sp1 and disrupts the recruitment of histone deacetylase (HDAC) to the promoter of hTERT and this leads to an increase in the expression of the gene." (PMID 27548225, 2016).